RNU6-922P (RNA, U6 small nuclear 922, pseudogene)
Gene: Small nuclear RNA gene on chromosome 3 (23,613,661 to 23,613,759, reverse strand). Ensembl gene ENSG00000252562.
Homologues: Orthologues: chimpanzee U6 (99% identical), macaque U6 (94% identical), dog U6 (82% identical), rabbit U6 (82% identical), pig U6 (81% identical), dog U6 (78% identical), rat LOC120101962 (72% identical), mouse Gm25898 (69% identical). Paralogues in human: RNU6-116P (86% identical), RNU6-1075P (84% identical), RNU6-1144P (84% identical), RNU6-326P (84% identical), RNU6-36P (84% identical), RNU6-46P (84% identical), RNU6-480P (84% identical), RNU6-560P (84% identical), RNU6-689P (84% identical), RNU6-83P (84% identical), RNU6-1 (83% identical), RNU6-1026P (83% identical), and 1285 more.